PINX1 (PIN2 (TERF1) interacting telomerase inhibitor 1)
Diseases named in the same sentence as PINX1 in open-access papers (continued):
Sharing a sentence is not in itself a finding about the gene and the disease.
tumor (continued). "As it has been documented that PinX1 could inhibit telomerase activity, shorten telomeres, and suppress tumor growth, we investigated whether PinX1 could influence tumor growth by regulating telomerase activity and the telomere length pathway." (PMID 24268029, 2013). "Our findings provide further support that PINX1 is a potential tumor suppressor." (PMID 22363464, 2012). "In short, the mechanisms by which PinX1 regulates telomerase/telomere in tumor cells are complex and may vary in different tumors." (PMID 22316341, 2012). "Loss of PinX1 has been found in a large variety of malignancies, however, its function in inhibiting telomerase activity of tumor cells is not well documented." (PMID 22316341, 2012). "Some studies indicate that PinX1 gene can inhibit telomerase activity and induce cell apoptosis, and expression of PinX1 is negatively correlated with hTERT expression and telomerase activity in tumor cells." (PMID 22316341, 2012). "Thus, almost all PinX1+/- mice spontaneously develop a range of aggressive epithelial cancers, which are unusual in mice, even after deleting many other tumor suppressors, but are known to have 8p23 LOH in humans." (PMID 22021332, 2011). "The recent results from my laboratory indicate that PinX1 is a major tumor suppressor at 8p23." (PMID 22021332, 2011). "Moreover, almost all PinX1 heterozygous knockout mice develop a range of epithelial malignancies, with multiple tumor types in the same mice, diverse cell morphologies/grades in one tumor type among mice, or even within individual tumors." (PMID 22021332, 2011). "Recent results have not only demonstrated that PinX1 is essential for maintaining telomeres at the optimal length, but also discovered that Pinx1 is a sought-after major tumor suppressor at human chromosome 8p23 that is essential for maintaining chromosome stability in vitro and in vivo." (PMID 22021332, 2011). "Moreover, targeting PinX1 enhanced radiotherapy-induced anti-tumor immunity." (PMID 38431575, 2024). "Therefore, low PINX1 expression promotes tumor proliferation, invasion, and migration." (PMID 30079348, 2018). "However, PinX1 protein expression differs greatly depending on the type of tumor tissue." (PMID 28978030, 2017). "Assuming a model where the 8p23 region is deleted in one copy of chromosome 8 in a tumor while the remaining copy contains insufficient PinX1 for inhibiting telomerase activity, we may expect that such a tumor will exhibit higher levels of telomerase activity than normal." (PMID 27556185, 2016). "Therefore, PinX1 is considered as telomerase inhibitor and tumor suppressor." (PMID 22316341, 2012). "This study reported the crystal structure of the TRF1TRFH-PinX1TBM complex and confirmed that PinX1 was recruited to the telomere by TRF1 predominantly via the binding to the F-X-L-X-P motif, highlighting its tumor-suppressive impact on CESC." (PMID 39634130, 2025). "Collectively, our findings identify PINX1 as a multifaceted partner of PARP1, crucial for safeguarding cells against genotoxic stress and emerging as a potential candidate for targeted tumor therapy." (PMID 39174499, 2024). "Our study revealed that PINX1 maintains cellular DNA damage repair capacity independently of telomerase inhibition, introducing a new facet to PINX1’s function as a partner of PARP1, whose deletion sensitizes tumor cells to PARPi." (PMID 39174499, 2024). "Moreover, down-regulation of PinX1 combined with RT could effectively enhance anti-tumor immunity." (PMID 38431575, 2024). "Thus, the upregulated pinX1 protein expression may contribute to inhibiting tumor growth." (PMID 35847001, 2022).
tumor (continued). "The aim of this study was to explore the mechanism through which PinX1 regulates epithelial–mesenchymal transition (EMT) and tumor metastasis in NPC and investigate its clinical significance and biological role with respect to disease progression." (PMID 32028978, 2020). "LPTS, also named PINX1, is a well-characterized tumor suppressor by inhibiting telomerase activity in multiple cancers." (PMID 29017500, 2017). "However, whether PinX1 is tumor-suppresive or promotive remains elusive." (PMID 24940406, 2014). "We also provided evidence that deletion may decrease mRNA expression of PINX1 and MSRA, which are the other two tumor suppressor candidates located on del8p23.1." (PMID 40699642, 2025). "Notably, PinX1 expression is diminished in HBV-related HCC, a reduction that facilitates tumor growth and enhances tumorigenic potential." (PMID 41383743, 2025). "PINX1 (PIN2/TRF1-interacting telomerase inhibitor 1) was initially identified as an interacting protein of TRF1 in the telomeric shelterin complex and recognized as a potent intrinsic telomerase inhibitor, hence considered a tumor suppressor." (PMID 39174499, 2024). "PINX1 (Pin2/TRF1 interacting protein X1, an intrinsic telomerase inhibitor and putative tumor suppressor gene) may represent a novel prognostic tumor biomarker." (PMID 30079348, 2018). "The disruption of the PinX1/NPM interaction may help to prevent telomerase activation and telomere maintenance and subsequently suppress the growth of certain tumor cell types." (PMID 28255170, 2017). "Further correlation analyses demonstrated that negative expression of PinX1 in our UCB cohort was significantly associated with advanced N classification, higher proliferation index, and tumor multiplicity." (PMID 24268029, 2013). "PinX1 may play important roles in NPC proliferation, migration and apoptosis and has application potential in tumor-targeted gene therapy." (PMID 22316341, 2012). "PinX1 was upregulated in CRC tumor tissues compared with non-tumorous colorectal tissues." (PMID 40639785, 2025). "The mechanism of PinX1 functioning in tumor cells has not been fully elucidated." (PMID 22316341, 2012). "However, the biological function of PinX1 on UCB tumorigenesis and tumor progression has not been characterized." (PMID 24268029, 2013).
adenocarcinoma (3 papers, 2014 to 2017). A common cancer characterized by the presence of malignant glandular cells. "Among all cases, PinX1 positivity was found to be more frequent in SCC (36 of 101 samples) than in adenocarcinoma (5 of 55 samples), suggesting that PinX1 expression may be associated with specific tissue types." (PMID 28815183, 2017). "In addition, the expression of PinX1 protein was examined by IHC on a TMA including 40 adenocarcinoma and 8 normal prostate tissues." (PMID 24936151, 2014).
PINX1 also shares sentences with these, for which no sentence is quoted: medulloblastoma (3 papers); diabetes mellitus (2); endocervical adenocarcinoma (2); systemic lupus erythematosus (2); thyroid cancer (2); acne (1); acute promyelocytic leukemia (1); Burkitt lymphoma (1); Cirrhosis (1); colorectal adenocarcinoma (1); esophageal cancer (1); head and neck squamous cell carcinoma (1); Insulin resistance (1); lung squamous cell carcinoma (1); lymphoma (1); metastasis (1); ovarian serous cystadenocarcinoma (1); rectum adenocarcinoma (1); squamous carcinoma (1); systemic sclerosis (1); type 1 diabetes mellitus (1); type II diabetes (1).